FGF2 (fibroblast growth factor 2)
Diseases named in the same sentence as FGF2 in open-access papers (continued):
Sharing a sentence is not in itself a finding about the gene and the disease.
myopia (continued). "Others were chosen for their potential biological relevance to myopia (FGF2, BDNF, and PAX6)." (PMID 17653045, 2007). "Instead, the results of genetic association study should be interpreted as the genetic variants at the FGF2 gene may not influence individual susceptibility to high myopia." (PMID 22393273, 2012). "Studies have shown that exogenous delivery of FGF2 may prevent the development of myopia in chick." (PMID 22393273, 2012). "Similar to our finding, FGF2 was significantly upregulated in the choroid/RPE of minus lens-treated eyes (i.e., eyes of induced myopia) of primate marmoset monkeys as compared with plus lens-treated fellow eyes (i.e., eyes of induced hyperopia)." (PMID 22393273, 2012). "Therefore, even though FGF2 may play a role in the myopia development, its genetic polymorphisms are unlikely to influence inter-individual susceptibility to high myopia." (PMID 22393273, 2012). "Recent research also suggests that fibroblast growth factor 2 (FGF-2) may regulate scleral structure and influence myopia progression in guinea pig models." (PMID 41438149, 2025). "We demonstrated that over-expression of HOXA9 in RPE cells could increase pro-myopia substances including TGF-β, FGF2, IGF1R and MMP2." (PMID 30674274, 2019). "Although there is no specific molecular marker for myopia, several molecules have been reported to be associated with myopia, which include TGF-β, FGF2, IGF signaling, HGF and MMP2." (PMID 30674274, 2019). "It needs to be noticed that the failure to identify significant SNPs at the FGF2 gene does not exclude the importance of this gene in the pathogenesis of myopia." (PMID 22393273, 2012). "We did not see evidence of the involvement of FGF2 in myopia in our sample." (PMID 17653045, 2007). "The specific mechanism by which FGF-2 might influence eye growth in experimental myopia has not been defined, but it may exert influence through regulation of scleral fibroblast proliferation or by stimulation of proteases during scleral reformation." (PMID 17653045, 2007). "In the tree shrew, the experimental induction of myopia did not result in differences in the level of scleral FGF-2 compared to control eyes, but there was upregulation of FGF receptor mRNA in experimental myopia." (PMID 17653045, 2007).
osteoarthritis (20 papers, 2013 to 2026). A noninflammatory degenerative joint disease occurring chiefly in older persons, characterized by degeneration of the articular cartilage, hypertrophy of bone at the margins and changes in the synovial membrane. "In vivo, FGF-2 is chondroprotective, as mice deficient in FGF-2 develop accelerated spontaneous and surgically induced osteoarthritis (OA)." (PMID 23740825, 2013). "Over follow-up, many CCD cases improved; however, in time-to-discharge analyses, higher IL-23, baseline rheumatoid arthritis, and higher VAS were associated with persistence, whereas higher FGF-2 and IL-4, arthrosis, and anti-CHIKV IgG were associated with earlier resolution." (PMID 41997930, 2026). "Similarly, the loss of HMW FGF2 offered protection in the model of osteoarthritis in a similar knockout model." (PMID 38438875, 2024). "Further analysis of these enriched pathways in injurious hydrostatic pressure highlighted differential expression of several genes known to be involved in osteoarthritis, such as Fgf2, Ep300, Ngf, Adam9, Igfbp3, Sox9, Comp, Col6a1, Col6a2 and Col11a1." (PMID 38144567, 2023). "In addition, several genes known to play a key role in progression of osteoarthritis (e.g., Fgf2, Ep300, Ngf, Adam9, Igfbp3, Sox9, Comp, Col6a1, Col6a2 and Col11a1) were modulated in our injurious hydrostatic pressure hip cap datasets, thereby validating this approach." (PMID 38144567, 2023). "Increased levels of VEGF-A, VEGFR1, PDGF-BB and FGF-2 and reduced VEGF-C in presurgery OA relative healthy subjects support a cartilage protective or disease-inducing role in osteoarthritis." (PMID 40688801, 2025). "In addition, a few randomized clinical trials performed in patients with periodontitis and osteoarthritis, two chronic inflammatory diseases with progressive tissue degeneration, demonstrated improved tissue repair upon the administration of recombinant human FGF-2." (PMID 36480517, 2022). "Our study has clearly demonstrated that circRNA-CDR1as functions as a sponge of miR-641 to promote osteoarthritis progression in human by regulating ECM homeostasis and inflammation via FGF-2 mediated MEK/ERK signaling pathway and could be utilized as a biomarker and target for OA therapy." (PMID 32099534, 2020). "If further studies confirm this regulatory role for FGF‐2 in osteocyte formation, we will be in a better position to understand the full repertoire of FGF‐2 on bone cell function which may provide insights into the etiology of skeletal disorders such as osteoporosis and osteoarthritis." (PMID 29215722, 2018).
periodontitis (20 papers, 2008 to 2026). An acute or chronic inflammatory process that affects the tissues that surround and support the teeth. "For reference, these correspond to a relatively moderate rank of 204 (FGF2), 645 (AZGP1) and 815 (BTC) among 3242 proteins that have shown any association with periodontitis." (PMID 40913361, 2026). "Similar to FGF2, but with less prior evidence in relation to periodontitis, AZGP1, a class I major histocompatibility complex domain glycoprotein, showed strong evidence at all phases of our analysis." (PMID 40913361, 2026). "The Open Targets association scores for these proteins were 0.57 for FGF2, 0.20 for AZGP1 and 0.15 for BTC, providing additional context for their potential biological relevance to periodontitis." (PMID 40913361, 2026). "This study identifies three circulating proteins—FGF2, AZGP1 and BTC—as causally associated with periodontitis, highlighting their potential as therapeutic targets." (PMID 40913361, 2026). "This suggests that the combined use of FGF-2 and CO3Ap would promote periodontal regeneration in severe bony defects of periodontitis patient." (PMID 37122358, 2023). "For example, the 6-year postoperative radiograph of a patient with aggressive periodontitis who was treated with FGF-2 revealed significant development of the alveolar bone in comparison with the first visit." (PMID 37122358, 2023). "For example, we found the hypo-methylated level of FGF2 and 4, both of which have been identified in other studies on both periodontitis and peri-implantitis." (PMID 35491409, 2022). "Of note, the target subjects in the clinical trials that evaluated FGF-2 were periodontitis patients with 2- or 3-walled vertical periodontal tissue defects." (PMID 35581234, 2022). "They hence concluded that topical application of FGF-2 can be efficacious in the regeneration of human periodontal tissue that has been destroyed by periodontitis." (PMID 22143705, 2012). "This study aimed to clarify the activity of FGF-2 in stimulating regeneration of periodontal tissue lost by periodontitis and to evaluate the safety of such stimulation." (PMID 18596969, 2008). "The purpose of this trial was to both clarify the activity of FGF-2 to regenerate periodontal tissue in periodontitis patients and to confirm drug safety." (PMID 18596969, 2008). "In short, none of the results of this particular clinical trial suggest any clinical problems concerning the safety of administering FGF-2 to patients with periodontitis." (PMID 18596969, 2008). "FGF-2 with CO3Ap enhances new bone formation and maintains existing bone adjacent to defect, which suggests that FGF-2 with CO3Ap could promote periodontal regeneration in severe bony defects of periodontitis patient." (PMID 39917693, 2024). "However, its efficacy when used in combination with FGF-2 in severe periodontitis models is not fully understood." (PMID 37122358, 2023). "In addition, we conducted clinical trials of intrabony defects in patients with periodontitis and demonstrated that FGF-2 was superior to the vehicle alone in terms of the percentage of bone fill in modified Widman periodontal surgery." (PMID 37122358, 2023). "To date, FGF-2 has been reported as efficacious in regenerating periodontal tissue in models of artificial defect of periodontal tissue in beagles and non-human primates (Macaca fascicularis) and in a model of surgically created periodontitis in beagles." (PMID 18596969, 2008). "Notably, recombinant human FGF‐2 (rhFGF‐2) is already approved in Japan for periodontitis therapy." (PMID 40913361, 2026). "Both FGF2 and 4 may be potential therapeutic strategies for the treatment of periodontitis." (PMID 35491409, 2022). "Further scrutiny examining colocalisation and directionality, and considering known protein interactions and prior evidence, suggested FGF2, AZGP1 and BTC as key targets for periodontitis." (PMID 40913361, 2026).
periodontitis (continued). "The activation of periodontal fibroblasts using fibroblast growth factor 2, FGF-2, can induce tissue regeneration in periodontitis." (PMID 36793548, 2022). "During the inflammatory response of periodontitis, the lymphocytes, macrophage and neutrophils are regulated by expression of multiple genes, such as ARHGAP10, ARPC1B, DOCK1, FGF2/4, TNFRSF1B, NXT1, and AHR, all of which were identified in our analysis." (PMID 35491409, 2022). "Therefore, our findings support a potential causal role of FGF2, AZGP1 and BTC in the aetiology of periodontitis, rather than quantifying the precise clinical magnitude of their effects." (PMID 40913361, 2026).
breast tumor (19 papers, 1997 to 2025). "Moreover, in a breast tumor mouse model obesity was associated with an increased release of FGF2 by adipocytes, whereas either the antidiabetic drug metformin or the inhibition of FGFR decreased the vessel density and restored the tumor sensitivity to anti-VEGF agents." (PMID 33081025, 2020). "Short SULF1 splice variants were predominant in breast tumors, promoting the growth of MDA‐MB231 and MCF7 cell lines derived from breast tumors induced by Fgf2 in vitro." (PMID 38590118, 2025). "Analysis of patient ER + breast tumor transcriptomes from the TCGA and METABRIC datasets demonstrated a strong positive association between expression of FGF2 and stemness signatures, which was further enhanced in tumors with high FGFR1 expression." (PMID 38553760, 2024). "In this regard, preclinical data have shown an increased FGF2 expression in breast tumors treated with antiangiogenic agents, whereas a suitable antitumor activity was obtained, inhibiting both the VEGFR and FGFR-mediated transduction pathways." (PMID 33081025, 2020). "In order to provide novel insights into the FGF2 regulation by estrogens within the tumor microenvironment, we sought to address whether estrogens may regulate FGF2 levels in ER-negative/ GPER-positive CAFs isolated from breast tumor patients (see material and methods section)." (PMID 30866584, 2019). "Immunization with FGF-2 peptides decreased CD4+CD25+FOXP3+ Treg cells and suppressed tumor vascularization and promoted apoptosis in grafted breast tumor mice model." (PMID 39232704, 2024). "Focusing on the functional liaison occurring between breast tumor cells and components of the surrounding stroma, we next assessed that S100A4 secreted by TNBC cells upon FGF2 treatment via RAGE endothelial tube formation and migratory responses in CAFs." (PMID 33946884, 2021).
fibrosis (19 papers, 2005 to 2025). the formation of excess fibrous connective tissue in an organ or tissue in a reparative or reactive process. "FGF2 was described as causative of cardiac disease and Fgf2 knockout or overexpressing mice showed its role in inducing cardiac fibrosis by increasing fibroblast proliferation and interstitial collagen deposition." (PMID 35957913, 2022). "CCL18-stimulated fibroblasts from fibrosis patients released significantly more FGF2 compared with CCL18-stimulated control fibroblasts." (PMID 38334630, 2024). "In vivo, the deletion or overexpression of FGF2 in transgenic animal models submitted to cardiac injury allowed the identification of various functions of FGF2 in cardiac fibrosis." (PMID 36675283, 2023). "Fibrosis also leads to an increase in cytokines, such as TGFβ1, fibroblast growth factor 2 (FGF2), and platelet-derived growth factor (PDGF)." (PMID 37187521, 2023). "One possible mechanism for silica-induced fibrosis is that silica exposure induces a toxic response in the pulmonary epithelium, leading to a reduction of the cell number and a subsequent compensatory increase in FGF-2 release." (PMID 19014534, 2008). "FGF-2 was produced in both bleached groups, and osteocalcin was present in large quantities 10 days after the clinical procedure, which may suggest a greater possibility of pulpal fibrosis and calcification because the role of the two mediators." (PMID 29898175, 2018). "Additionally, in the in vivo studies using mice and rats, anti-FGF2 aptamer, umedaptanib pegol (formerly called RBM-007), inhibits not only FGF2-induced angiogenesis but also laser-induced CNV, and CNV with fibrosis." (PMID 38036609, 2024).
brain tumors (18 papers, 2008 to 2025). "Fibroblast growth factor-2 plays a critical role in nervous system development, and dysregulated expression is implicated in the pathogenesis of brain tumours." (PMID 19018263, 2008). "Among them, FGF2 seems to be the most important one when it comes to the regulation of angiogenesis in brain tumors." (PMID 33036204, 2020). "Additionally, it has been reported that soluble VEGFR-1 (sVEGFR-1), but not sVEGFR-2, -3, and the primary fibroblast growth factor (bFGF, alternatively known as FGF-2) increased in preoperative serum samples from newly diagnosed patients with brain tumor." (PMID 34210107, 2021). "In addition, FGF2 (bFGF) is overexpressed in pilocytic astrocytomas more than in other brain tumors and compared to normal brain tissue." (PMID 30279357, 2018). "Other growth factors involved in brain tumors are insulin-like growth factors, IGFs fibroblast growth factor 2, FGF2, ciliary neurotrophic factor, CNTF, hepatocyte growth factor/scatter factor, HGF/SF, vascular endothelial growth factor, VEGF, and transforming growth factor-β, TGF-β." (PMID 22091432, 2011). "Finally, FGF2 has been proven to directly induce VEGF expression and production, which is the master potentiator of angiogenesis in brain tumors." (PMID 33036204, 2020). "We finally investigated the dynamic behavior of our cell lines cultured under differentiating (diff) conditions (medium supplemented with 10% FBS without FGF2 and EGF) that let them loss their stem cell properties including their capacity to generate brain tumors in immunodeficient mice." (PMID 33128011, 2020).
Hyperglycemia (18 papers, 2005 to 2025). An increased concentration of glucose in the blood. "Several mechanisms have been proposed to explain this poor outcome, including increased tumor metastasis and progression via fibroblast growth factor 2, changes in endothelial cell function, and alterations to the baseline membrane caused by hyperglycemia." (PMID 37654164, 2023). "A Fluc/Rluc reporter containing the Fgf2 IRES was knocked-in to demonstrate differential effects of hyperglycemia depending on tissue type." (PMID 34068921, 2021). "Furthermore, local hyperglycemia and advanced glycation end products (AGEs) in diabetic patients may promote glycosylated FGF-2 production, which inhibits the proliferation of endothelial cells and has negative effects on wound healing." (PMID 37371653, 2023). "It was reported that hyperglycemia inhibits the proliferation of HUVESCs stimulated by FGF2 but did not change the vascular endothelial growth factor-induced angiogenesis, which is controlled by extracellular signal-regulated kinases 1/2 (ERK1/2)." (PMID 34944571, 2021).
ischemic heart disease (18 papers, 2012 to 2025). "One study showed that increased plasma FGF-2 levels might even be a risk biomarker for coronary heart disease occurrence in adult men with DM type 2." (PMID 37371653, 2023). "For example, in the phase II FGF Initiating RevaScularization Trial (FIRST), a double-blind, randomized, and controlled study, a single intracoronary infusion of FGF2 was given to patients with severe coronary artery disease." (PMID 35295649, 2022). "But, in the context of ischemic heart disease, inhibition of FGF-2 signaling may be detrimental, since an angiogenic effect by Lo-FGF-2 upregulation may be desirable." (PMID 37443814, 2023). "Currently, there are still some clinical trials to be processed, for example, a clinical study of Kangfuxin (a clinically approved extract from Periplaneta americana) and FGF2 in promoting the healing of donor site and FGF1 for the treatment of coronary heart disease." (PMID 36102060, 2022).